SOD1-DT (SOD1 divergent transcript)
Synonyms: AP000253
Gene: Long non-coding RNA gene on chromosome 21 (31,624,034 to 31,659,500, reverse strand). Ensembl gene ENSG00000234509.
Diseases named in the same sentence as SOD1-DT in open-access papers:
SOD1-DT is named in the same sentence as 1 disease in open-access papers, as found by Europe PMC text mining. Sharing a sentence is not in itself a finding about the gene and the disease.
SOD1-DT shares sentences with these, for which no sentence is quoted: infection (1 paper).